GSDMD (gasdermin D)
Diseases named in the same sentence as GSDMD in open-access papers (continued):
Sharing a sentence is not in itself a finding about the gene and the disease.
myocardial ischemia (14 papers, 2021 to 2025). A disorder of cardiac function caused by insufficient blood flow to the muscle tissue of the heart. "Our study was designed to elucidate the crucial role of oridonin during myocardial ischemia-reperfusion injury and uncover its underlying molecular mechanism via the regulation of GSDMD-mediated pyroptosis." (PMID 36421808, 2022). "Exhibits cardioprotective characteristics by suppressing NLRP3 inflammasome activation and GSDMD-mediated pyroptosis in cardiomyocytes, presenting potential uses for myocardial ischemia/reperfusion damage." (PMID 40191425, 2025). "In our previous study, we revealed GI‐Y1 as an inhibitor of GSDMD via GSDMD‐N‐based virtual screening and confirmed the protective effect of GI‐Y1 on myocardial ischemia/reperfusion injury." (PMID 40045452, 2025). "In our previous study, we identified GI‐Y1 as an inhibitor of GSDMD via structure‐based virtual screening and revealed the inhibitory activity of GI‐Y1 in cardiac pyroptosis and myocardial ischemia/reperfusion injury." (PMID 40045452, 2025). "For example, GSDMD-mediated pyroptosis promotes myocardial ischemia/reperfusion injury; inflammasome-mediated pyroptosis is the main player in development of diabetic cardiomyopathy." (PMID 37158944, 2023). "GSDMD is involved in many pathophysiologic processes, including septic shock, spinal cord injury, and myocardial ischemia/reperfusion (I/R) injury." (PMID 36807553, 2023). "Although the expression of caspase-1/11 and IL-1β/IL-18 is controversial due to the differences in subjects and the time of ischemia, consistent with our study, the expression of GSDMD and GSDMD-N increased during myocardial ischemia." (PMID 35783187, 2022). "Collectively, our results show that oridonin ameliorates myocardial ischemia-reperfusion injury by affecting GSDMD-mediated pyroptosis." (PMID 36421808, 2022). "Emodin was previously reported to strongly inhibit GSDMD-mediated pyroptosis induced by myocardial ischemia/reperfusion in cardiomyocytes." (PMID 35721108, 2022). "Intriguingly, both expression and activation of GSDMD in heart were remarkably enhanced in response to myocardial ischemia/infarction in left anterior descending (LAD) ligation–operated wild type (WT) mice, as early as 24 hours after AMI." (PMID 34752417, 2022). "In our study, GSDMD-mediated pyroptosis is the main mechanism explored in myocardial ischemia-reperfusion injury." (PMID 36421808, 2022). "Herein, we further verified the detailed function of AQP4 in the mouse model of myocardial ischemia-reperfusion injury, which mainly via a mechanism of GSDMD-dependent pyroptosis approach." (PMID 34657556, 2021). "Furthermore, GSDMD‐mediated pyroptosis in cardiomyocytes is considered a pivotal event in myocardial ischemia." (PMID 40636987, 2025). "However, the role of pyroptosis executive protein GSDMD in myocardial ischemia injury is less reported." (PMID 35783187, 2022).
inflammatory bowel disease (13 papers, 2021 to 2026). A spectrum of small and large bowel inflammatory diseases of unknown etiology. "Gasdermin D (GSDMD), a protein belonging to the gasdermin protein family, plays a role in inflammatory cell death, and activation of GSDMD has been shown to be a component of the pathogenesis of inflammatory bowel disease." (PMID 40418140, 2025). "Gasdermin D (GSDMD), a protein belonging to the gasdermin protein family, plays a role in inflammatory cell death, and activation of GSDMD has been shown to be a component of inflammatory bowel disease pathogenesis." (PMID 40418140, 2025). "In conclusion, we systematically summarized the landscape of pyroptosis in inflammatory bowel disease and identified AIM2, CASP1, CASP5, GSDMD, and NLRP3 as hub genes." (PMID 37740137, 2023). "In addition, GSDMD, as a family of pore-forming proteins involved in the immune response, has been recently described as participating in the immune regulation in various inflammatory disease models, including inflammatory bowel disease (IBD), sepsis, and autoimmune diseases." (PMID 34733156, 2021).
liver fibrosis (13 papers, 2020 to 2025). "In methionine-and-choline-deficient (MCD)-fed mice, knockout of GSDMD reduced liver triglycerides and significantly alleviated liver inflammation and liver fibrosis, suggesting that GSDMD plays an important role in the development of steatohepatitis." (PMID 37275856, 2023). "The identified circulating GSDMD had the highest diagnostic value for the diagnosis and staging of liver fibrosis, suggesting that GSDMD may have the potential to be an alternative biomarker for liver fibrosis evaluation." (PMID 36429008, 2022). "Conversely, the inhibition of caspase-1 and gasdermin D (GSDMD) can suppress pyroptosis and mitigate the progression of liver fibrosis." (PMID 40406118, 2025). "For instance, exosomes derived from bone marrow mesenchymal SCs mitigate liver fibrosis in cirrhosis rat models by inhibiting PCNA/NLRP3/caspase 1/GSDMD-mediated pyroptosis." (PMID 40667485, 2025). "It has been reported that GSDMD-mediated lipogenesis and NF-ĸB signaling play a key role in the development of non-alcoholic steatohepatitis; GSDMD-NT, the activation form of GSDMD, is positively correlated with liver fibrosis and NAFLD." (PMID 35565726, 2022). "More importantly, the identified pyroptosis-related indicator GSDMD has the potential to be an alternative biomarker for liver fibrosis evaluation." (PMID 36429008, 2022). "More importantly, circulating GSDMD had the optimal predicting value for liver fibrosis progression." (PMID 36429008, 2022). "Here, elevated levels of the pyroptosis-related indicators GSDMD, IL-1β, and IL-18 were confirmed in both clinical specimens from liver fibrosis patients and CCl4-induced liver fibrosis mouse models." (PMID 36429008, 2022). "Here, augmented levels of pyroptosis-related indicators GSDMD, IL-1β, and IL-18 were verified in both liver fibrosis patients and CCl4-induced fibrotic mouse model." (PMID 36429008, 2022). "Immunohistochemical (IHC) analysis revealed that the expression of hepatic GSDMD, IL-1β, and IL-18 was significantly upregulated in patients with liver fibrosis compared to HCs." (PMID 36429008, 2022). "Furthermore, serum S100A8 and pyroptosis-related indicators GSDMD, IL-1β, and IL-18 levels were all gradually augmented during the progression of the liver fibrosis model." (PMID 36429008, 2022). "The identified GSDMD has the potential to be a biomarker for liver fibrosis evaluation." (PMID 36429008, 2022). "Moreover, consistent with the human data, GSDMD and IL-1β expression were significantly increased in the liver from the liver fibrosis mouse model compared with the control." (PMID 36429008, 2022). "Furthermore, serum levels of GSDMD, IL-18, and IL-1β were markedly enhanced in mouse models of liver fibrosis." (PMID 36429008, 2022). "In addition, we identified that the pyroptosis-related indicator GSDMD may be a potential biomarker for the occurrence and progression of liver fibrosis." (PMID 36429008, 2022). "This study summarizes approaches that mitigate liver fibrosis/cirrhosis through the anti-pyroptosis pathway, including inhibitors targeting NLRP3, GSDMD, and caspases in the pyroptosis pathway, natural plant compounds and biomaterials (SCs and exosomes)." (PMID 40667485, 2025). "The expression of NLRP3, ASC, caspase-1p20, and GSDMD was reduced by Pip treatment, which resulted in the inhibition of NLRP3 activation in pyroptosis and led to improved liver fibrosis." (PMID 38547097, 2024). "Liu and colleagues found that liver expression of GSDMD, NLRP3, caspase-1 and IL-1β increased in Schistosoma japonicum-infected mice, leading to exacerbation of hepatic fibrosis." (PMID 38086792, 2023). "Ursolic acid inhibits KC pyroptosis in liver fibrosis in vitro and in vivo by suppressing the protein expression of pyroptosis-related indicators (NLRP3, pro-caspase-1, cleaved caspase-1, GSDMD, GSDMD-N, and IL-1β) in the NOX2/NLRP3 inflammasome signaling pathway." (PMID 40667485, 2025).
liver fibrosis (continued). "Pyroptosis and hepatic fibrosis were induced by activating NOD-like receptor family pyrin domain containing 3 (NLRP3) inflammasomes in primary hepatocytes from mice, and blocking caspase-1 and GSDMD inhibited pyroptosis and hepatic fibrosis." (PMID 38086792, 2023). "Based on the role of S100A8-elicited NLRP3 pyroptosis in liver fibrosis, we chose a well-defined cohort of liver fibrosis patients to assess the clinical importance of circulating S100A8, GSDMD, IL-1β, and IL-18 for predicting the occurrence and progression of disease." (PMID 36429008, 2022). "Since NSA is also reported as inhibitor of GSDMD-mediated pyroptosis, which is also involved in liver injury/fibrosis, we consider that NSA is likely to attenuate BDL-induced liver fibrosis via inhibiting pyroptosis (maybe not necroptosis)." (PMID 36859525, 2023).
multiple sclerosis (13 papers, 2020 to 2024). A progressive autoimmune disorder affecting the central nervous system resulting in demyelination. "As Gasdermin D expression has been associated with white matter loss in multiple sclerosis as well as in experimental autoimmune encephalomyelitis, we used a semi-quantitative analysis to assess Gasdermin D expression in our two dog models." (PMID 33837260, 2021). "Microglia/macrophages in the central nervous system (CNS) undergo GSDMD-associated pyroptosis in multiple sclerosis (MS) and its animal model experimental autoimmune encephalomyelitis (EAE) but the contribution of other cell death pathways to this phenomenon is unknown." (PMID 32861242, 2020). "Further, GSDMD inhibitors have been described, of which dimethyl fumarate is already being used in the treatment of multiple sclerosis." (PMID 36762431, 2023). "Dimethyl fumarate, the FDA-approved drug for multiple sclerosis, induces succination of GSDMD, blocking the interaction of GSDMD with caspases and subsequent cell death." (PMID 37515138, 2023). "Evidence of caspase‐1 activation and gasdermin D‐mediated pyroptosis has also been observed in the CNS of multiple sclerosis patients and in animal models, further implicating NLRP3 involvement." (PMID 35137954, 2022). "Furthermore, we directly evaluated the therapeutic effect of GSDMD inhibition on UPEC-induced orchitis in a mouse model by administering DMF, an inhibitor of GSDMD activation that has been approved for the treatment of multiple sclerosis." (PMID 38177538, 2024). "Administration of DMF to mice alleviated inflammation in models of multiple sclerosis and familial Mediterranean fever, which indicated that GSDMD succinate prevents its interaction with caspases, limiting its processing, oligomerization, and capacity to induce cell death." (PMID 36159393, 2022). "Furthermore, dimethyl fumarate (used as an immunomodulator in multiple sclerosis) also covalently binds GSDMD thereby inhibiting pyroptosis in vitro and in vivo in a mouse model of LPS-induced shock." (PMID 35625908, 2022). "Meanwhile, GSDMD is the executioner of pyroptosis in response to inflammasome activation, is present in CNS microglia and oligodendrocytes, and has been shown to play a critical role in neuroinflammation in the pathogenesis of multiple sclerosis and experimental autoimmune encephalomyelitis." (PMID 37921870, 2023). "For instance, in the case of multiple sclerosis, the release of TNF-α from activated myeloid cells contributes to GSDMD upregulation, which further promotes pyroptosis in oligodendrocytes and demyelination." (PMID 35350377, 2022).
ischemia (12 papers, 2020 to 2025). A hypoperfusion of the BLOOD through an organ or tissue caused by a PATHOLOGIC CONSTRICTION or obstruction of its BLOOD VESSELS, or an absence of BLOOD CIRCULATION. "Levels of cleaved caspase-11 and the N-terminal fragment of gasdermin D (GSDMD-N) in ischemic myocardial tissue increased progressively over time after ischemia/reperfusion." (PMID 40134584, 2025). "It is reported that H2S can reduce neuronal inflammation by inhibiting the NLRP3/caspase-1/GSDMD signaling pathway in ischemia/reperfusion brain injury." (PMID 37445920, 2023). "NaHS use reduced the pyroptosis of retinal cells and brain neurons through inhibition of the NLRP3/caspase-1/GSDMD signaling pathway in an ischemia/reperfusion injury model." (PMID 37445920, 2023). "Here, we report a specific pattern of GSDMD-protein expression in the peritubular compartment of mice that underwent bilateral ischemia and reperfusion injury (IRI)." (PMID 36109515, 2022). "Elevated expression of GSDMD and GSDMD p30, the pore‐forming subunit, was evident in the peri‐ischemic region on days one and three post‐ischemia." (PMID 32343048, 2020). "To assess the involvement of pyroptosis in ischemic brain damage, we quantified the expression of the pore‐forming subunit GSDMD on days one, three, and seven post‐ischemia by WB and IF, compared with the sham‐operated group." (PMID 32343048, 2020). "Since the expression and processing of GSDMD peaked on day three, we made a comparison between post‐ischemia and sham‐operated groups on that day." (PMID 32343048, 2020). "However, knockout of GSDMD aggravated myocardial injury after 45 min ischemia, followed by 4 w reperfusion." (PMID 35783187, 2022). "However, whether GSDMD participates in myocardial ischaemia/reperfusion injury (MI/RI) remains poorly understood." (PMID 36217543, 2022). "In a mouse ischemia/reperfusion model, hypoxic preconditioning decreased pyroptosis to prevent inflammatory injury by inhibiting the expression of the NLRP3 inflammasome and the related proteins Caspase-1 and Gasdermin D." (PMID 38317957, 2024).
melanoma (12 papers, 2022 to 2025). A malignant, usually aggressive tumor composed of atypical, neoplastic melanocytes. "In addition, analysis of the TCGA human melanoma patient cohort revealed that high expression of GSDMD is associated with a significant overall survival benefit." (PMID 36323669, 2022). "Consistently, analysis of a second dataset involving 68 advanced melanoma patients treated with nivolumab, either post-ipilimumab or ipilimumab-naïve, demonstrated that high GSDMD expression predicted inferior survival outcomes (HR = 1.8781, p = 0.014)." (PMID 40491921, 2025). "Along those lines, myeloid-specific KO of Gasdermin D (GSDMD) boosted anti-tumor immunity in anti-PD-L1-treated B16F10 melanoma-bearing mice, as characterized by elevated infiltration of CD4+ and CD8+ T cells, but also B cells and natural killer (NK) cells." (PMID 40098954, 2025). "The RNA-seq data for Melanoma treated with anti-CTLA-4 therapy shows that the expression level of GSDMD significantly decreased after treatment (log2FC = -1.1007), with a p-value of 0.021." (PMID 40491921, 2025). "Epigenetic therapy can upregulate the expression of specific proteins, such as upregulating GSDME and ORZ levels using DNA methyltransferase inhibitor DAC, as well as upregulating GSDMD levels in melanoma." (PMID 39221221, 2024). "Our results present compelling evidence for the GSDMD cleavage and induction of GSDMD -mediated pyroptosis in murine melanoma cells when attacked by antigen-specific cytotoxic T lymphocytes." (PMID 36323669, 2022). "Blocking GSDMD-mediated pyroptosis partially rescues the growth defects of Mll4−/− melanoma cells and markedly increases the tumor burden in immune-competent mice treated with or without PD-1 blockade antibody." (PMID 36323669, 2022). "Conversely, RNA-seq data from melanoma patients undergoing anti-CTLA-4 therapy revealed a significant downregulation of GSDMD post-treatment (log2FC = -1.1007, p = 0.021), suggesting dynamic modulation of GSDMD in response to distinct immune checkpoint inhibitors." (PMID 40491921, 2025). "Indeed, pharmacologic blocking of GSDMD -mediated pyroptosis abrogates immunotherapeutic sensitivity of Mll4−/− melanomas to anti-PD-1 treatment." (PMID 36323669, 2022). "Our data further indicated that GSDMD-mediated pyroptotic cell death is immunostimulatory and is indispensable for the increased spontaneous anti-tumor immune response and the enhanced sensitivity to anti-PD-1 blockade in Mll4−/− melanomas." (PMID 36323669, 2022). "The combinatory therapy of immunostimulatory cytokines IL-1β, IL-18, or IL-12 with GSDMD-based pyroptosis while not causing systemic adverse effects generates a robust antitumor response, ultimately leading to long-term remission in mouse melanoma model." (PMID 39737979, 2024). "Therefore, therapy targeting ASC, CASP1, and GSDMD in TIDCs may also serve to convert cold melanomas to hot melanomas." (PMID 37046775, 2023). "However, whether GSDMD activation and GSDMD-dependent NETs is involved in melanoma metastasis are unknown." (PMID 36132145, 2022). "Intriguingly, GSDMD exhibits opposing effects in CRC and SKCM—serving as a positive prognostic marker in CRC while suppressing proliferation and metastasis in melanoma." (PMID 40491921, 2025). "When applied to relatively large tumors, the induction of ICD with GSDMD variants proved to be potent in B16F10 melanoma tumor surveillance with around 20–25% long-term survivors regardless of whether NT GSDMD was introduced or GSDMD cleavage was induced by the addition of small molecule." (PMID 39737979, 2024). "For example, CASP4, NLRP1, MEFV, IL18, and NINJ1 correlated positively with GSDMD in metastatic melanoma patients but not in primary melanoma patients." (PMID 38229080, 2024).
melanoma (continued). "In this study, we found that IVM significantly inhibited the transformation of melanoma We also identified a new mechanism, namely the formation of IVM/GSDMD dependent network, and the recently discovered IVM reconstruction of the micro immune environment for lung tumors." (PMID 36132145, 2022).